RAC2 (Rac family small GTPase 2)
Diseases named in the same sentence as RAC2 in open-access papers (continued):
Sharing a sentence is not in itself a finding about the gene and the disease.
tumor (continued). "H & E staining clearly shows a marked increase in tumor invasion within the muscularis layer in WT animals as compared to Rac2-/- animals injected with LLC tumors." (PMID 24770346, 2014). "As tumor growth, angiogenesis and invasion are prerequisites to tumor progression and metastasis, we first examined the effects of homozygous Rac2 deletion on these three phenotypes." (PMID 24770346, 2014). "This prompted us to determine if the reduced tumor growth observed in the Rac2-/- mice reflected an alteration in tumor-induced angiogenesis." (PMID 24770346, 2014). "Since Rac2 is expressed in a number of hematopoietic lineages and in endothelial cells, we sought to determine if the tumor growth, metastasis and M1-M2 specific defects noted in the Rac2-/- mouse model were macrophage autonomous." (PMID 24770346, 2014). "In the present study, we provide a novel role of macrophage Rac2 in controlling tumor growth and M2 macrophage differentiation." (PMID 24770346, 2014). "The microarray studies conducted on BMDMs isolated from Rac2-/- mice provide evidence that Rac2 controls expression of genes related to invasion and angiogenesis which supports the RT PCR data obtained from tumor derived Mθs in WT vs Rac2-/- mice." (PMID 24770346, 2014). "Our present studies demonstrate that specific α4β1 integrin in macrophages regulates, tumor growth and metastasis and that the mechanism for α4β1 induced migration and M2 macrophage differentiation requires Rac2." (PMID 24770346, 2014). "Using a genetic approach, combined with syngeneic and orthotopic tumor models we demonstrate that Rac2-/- mice display a marked defect in tumor growth, angiogenesis and metastasis." (PMID 24770346, 2014). "The pathway extends from the cell surface receptors MCSF receptor and integrin α4β1 to the activation of the Rac2 to control differentiation of M2 macrophage differentiation, tumor growth and metastasis in vivo." (PMID 24770346, 2014). "Moreover, TIP analysis of MP3‐dominant tumours revealed CD8 T cell infiltration in tumours with high RAC2 expression." (PMID 40292733, 2025). "Furthermore, additional study is warranted evaluating the role of P-Rex1 in additional cell lines and on modulation of the tumor microenvironment and stroma, including regulation of Rac2 and subsequent effects on macrophage differentiation." (PMID 38884093, 2024). "Moreover, RAC2 plays a significant role in regulating the transition of macrophages from the M1 to M2 phenotype, a process crucial for tumor progression, angiogenesis, and metastasis." (PMID 39273699, 2024). "We next evaluated the effect of NEDD4L-mediated RAC2 ubiquitination on tumor cell growth." (PMID 39596003, 2024). "Interestingly, the heterologous Rac2-specific 22894 TCR-transduced T cells showed greater efficacy in tumor regression compared to the Rac1-specific TCR 5934." (PMID 36875127, 2023). "These contradictory results may be due to the fact that the development of tumors was the result of a combination of effects, and analysis of a single molecule was insufficient to elucidate the overall immune role of RAC2 in tumor microenvironment." (PMID 37214785, 2023). "In addition, to further explore the impact of RAC2 on tumor etiology or pathogenesis, we conducted the enrichment analysis on RAC2." (PMID 37214785, 2023). "Basing on these findings, we speculate that RAC2 is likely to regulate the radiosensitivity of the tumor cells by modulating the activity of NADPH oxidase." (PMID 31281584, 2019). "The present study began with our initial observation that the provisional integrins, α4β1/αvβ3 induced migration requires a specific isoform of Rac, Rac2, in macrophages and that this pathway regulated the tumor metastasis and alternative activation of M2 macrophages in vivo." (PMID 28817691, 2017).
tumor (continued). "For the mechanism, the decrease of TAMs and TANs could be derived from the diminished presence in tumor tissues of cytokines GM-CSF and IL-8, as well as a decreased gene expression of the small GTPase Rac2, key for leukocyte chemotaxis." (PMID 27851813, 2016). "Hence, we investigated if there is any defect in the recruitment of macrophages in the tumor in these Rac2-/- mice or if this GTPase modulates the phenotype of macrophages recruited into the tumor via some other mechanism?" (PMID 24770346, 2014). "In addition, from our data in Rac2-/- mice, we conclude that macrophage entry into the tumor is likely necessary butnot sufficient to drive M1 to M2 differentiation of TAMs." (PMID 24770346, 2014). "On the basis of these observations and the importance of M2 macrophages in tumor progression, we hypothesized that Rac2 is somehow regulating the transition of macrophages into the M2 phenotype in vitro." (PMID 24770346, 2014). "Our results clearly establish a requirement for Rac2 in tumor growth, invasion and metastasis." (PMID 24770346, 2014). "These interesting observations prompted us to conduct mRNA gene expression and metabolomic studies on Rac2-/- vs. WT BMDMs to identify other components downstream of Rac2 that might be required for tumor growth, metastasis and polarization of macrophages." (PMID 24770346, 2014). "Since macrophage entry into the tumor microenvironment (TME) in the Rac2-/-mice is normal, as revealed by F4/80 quantification and FACS analysis, the data suggest an alternative mechanism for the tumor growth and metastatic defect observed in the Rac2-/- mouse." (PMID 24770346, 2014). "Tumor invasion is a preliminary step for metastasis; hence we used both experimental as well as spontaneous metastasis mouse models to examine metastasis in the Rac2-/- mice." (PMID 24770346, 2014). "These three independent experimental observations and datasets support the hypothesis that reversion of tumor growth and metastasis in Rac2-/- mice is a macrophage autonomous phenotype." (PMID 24770346, 2014). "Especially, we initially identified the importance of RAC2, one of the NETs‐related signature genes, in OvCa metastasis by inducing NETs formation, which could provide hints towards the anti‐tumour response of NETs, though definite mechanism needs further exploration." (PMID 39730971, 2024). "Finally, we screened the tumor types with RAC2 gene expression and OS for further study." (PMID 37214785, 2023). "Finally, to further compare whether RAC2 expression differed in tumor tissues and corresponding normal tissues, we first confirmed from the HPA database that RAC2 was highly expressed in BRCA, COAD, LIHC, LUAD, and PRAD." (PMID 37214785, 2023). "KEGG pathway analysis showed that RAC2 may be involved in “cytokine receptor interaction,” “chemokine signaling pathway,” “antigen processing and presentation,” and other related pathways in the process of tumor pathogenesis." (PMID 37214785, 2023). "However, the functional relation between RAC2 and tumor and whether it drives or inhibits tumor pathogenesis remained poorly understood." (PMID 37214785, 2023). "Thus, we believe RAC2 has a significant effect in tumor growth, angiogenesis, and metastasis." (PMID 28029655, 2017). "Collectively, these genomic and metabolomic data serve to identify new biomarkers for M1 and M2 Mθdifferentiation and further support our hypothesis that Rac2 plays a unique role in transition of macrophages to anti-inflammatory M2 phenotype to promote tumor metastasis." (PMID 24770346, 2014). "To further support our model for how the provisional integrins are linked to tumor growth, metastasis and M2 macrophage differentiation, we provide evidence that MCSF receptor cosignals through α4β1 integrin to promote these events by specifically activating Rac2." (PMID 24770346, 2014). "RAC2 contributes to EMT and metastasis by mediating cytoskeletal reorganization and activating pro-tumor pathways like PI3K/AKT and JNK/ZEB1." (PMID 40072059, 2025).
tumor (continued). "This review highlights the molecular mechanisms by which RAC2 and PTTG1 influence tumorigenesis and describes their potential and efficacy as prognostic biomarkers and therapeutic targets in managing various neoplasms." (PMID 40072059, 2025). "Especially, RAC2, one of the NETs‐related signature genes, was predominantly related to NET formation, thus providing hints towards the anti‐tumour response mechanism of NETs in OvCa." (PMID 39730971, 2024). "Therefore, RAC2 may play a tumor-suppressive role in immune cell infiltration." (PMID 37214785, 2023). "To investigate the differences in therapeutic outcome when targeting Rac1P29S+ MC703-FSG tumors with either Rac1- or Rac2-specific T cells, we monitored the human TCR-transduced HHD+ T cells after transfer into tumor-bearing mice in the second experiment." (PMID 36875127, 2023). "Many studies indicated that the expression of these proteins, including RHOA, RHOC, RAC1, RAC2 and CDC42 are upregulated and/or their activities are dysregulated through GEFs, GAPs or GDIs in tumor tissue." (PMID 33406731, 2021). "Although RAC2 has been studied for the regulation of activity of NADPH oxidase, the studies of the relationship between RAC2 and radiosensitivity of tumor cells are limited." (PMID 31281584, 2019). "In contrast, the expressions of RAC2 (p = 0.0405), ZAP70 (p = 0.0121), IL2RG (p = 0.0175) and CD247 (p = 0.0112) were downregulated in tumour tissues." (PMID 29967488, 2018). "We also confirmed that RAC2 is co-expressed with CD34-positive cells and that RAC1 is strongly expressed at the tumor-stroma border of Tgfbr2 cKO SCC." (PMID 28219480, 2017). "Collectively, our findings demonstrate a macrophage autonomous process by which the Rac2 GTPase is activated downstream of the α4β1 integrin and the MCSF receptor to control tumor growth, metastasis and macrophage differentiation into the M2 phenotype." (PMID 24770346, 2014). "Our current results establish that the Rac2 GTPase controls tumor growth, invasion and metastasis and that Rac2 is activated downstream of the α4β1integrin, the CSF1 receptor and that Rac2 is required for macrophage differentiation." (PMID 24770346, 2014). "In contrast, RAC2‐high tumours (MP3‐dominant) showed lacked FAP expression and maintained abundant CD8 T cell infiltration." (PMID 40292733, 2025). "Furthermore, both RAC2 and PTTG1 promote the formation of a vascular niche by upregulating VEGF and contributing to angiogenesis, which further supports tumor growth and metastasis." (PMID 40072059, 2025). "Other genes: BTG1, CD24, KRT19, RAC2 and RGS1 were significantly upregulated in tumour samples." (PMID 39098994, 2024). "The exclusive selection of antigen-negative tumor cells by the heterologous Rac2-specific T cells that led to tumor relapse in our in vivo model argues for a strong T cell pressure." (PMID 36875127, 2023). "RAC2 was positively correlated with MHC/HLAI expression; therefore, it may be effective in tumor immunotherapy in inhibiting immune escape." (PMID 37214785, 2023). "While in vitro the Rac1-specific 5934 TCR-transduced T cells performed slightly better in cytotoxicity and IFNγ release, the Rac2-specific 22894 TCR-transduced T cells expanded significantly better in vivo and induced more potent regression of the Rac1P29S expressing tumor cells." (PMID 36875127, 2023). "Some experimental studies on RAC2 mainly focus on individual tumor types, and the existing studies do not comprehensively examine multiple tumor types at the same time to determine their similarities and differences." (PMID 37214785, 2023). "Our further research suggested that WAKMAR2 is crucial in regulating the tumour microenvironment and may function by regulating immune-related genes, including IL27RA, RAC2, FABP7, IGLV1-51, IGHA1, and IGHD." (PMID 34321580, 2021).
tumor (continued). "Knockdown of Rac3, but not of Rac1 or Rac2, induces autophagy in different tumor cell lines, including prostate cancer PC3 and breast cancer MDA-MB-231 cells that express low levels of Rac3." (PMID 31514269, 2019). "Immunofluorescence staining confirmed that TGFβ-deficient DMBA-induced skin SCC does not express RAC1 and RAC2 in contrast to anorectal SCC, where these proteins are found at the invasive front of the tumor." (PMID 28219480, 2017). "Recently, our laboratory has shown that Rac2-/- mice are defective in tumor growth and the absence of Rac2 skews macrophages towards classical M1 activation." (PMID 28817691, 2017). "We confirmed these results via Western blotting analysis of tumor cells expressing AFAP1-AS1 siRNA, and found that RhoA, Rac2, Rab10, Rab11a, Rhogdi and Pfn1 were significantly upregulated, but RhoC, Rab11b and Lasp1 were significantly downregulated in NPC cell lines." (PMID 26246469, 2015). "The expression levels of tumor promoting M2 markers: Cox 2, uPA, MMP9, MMR, arginase and VEGF are significantly higher in Mθs sorted from LLC tumors of WT while Mθs sorted from Rac2-/- mice displayed higher levels of proinflammatory cytokines, which are considered as M1 markers; IL1 and TNFα." (PMID 24770346, 2014). "Under these conditions, WT and not Rac2-/- Mθ injections lead to reversal of tumor growth defect in Rac2-/- mice in vivo." (PMID 24770346, 2014). "As predicted, the injection of WT BMDMs and not WT GBMDMs or Rac2-/- BMDMs increased tumor growth, metastasis and polarization of macrophages to M2 phenotype in Rac2-/- animals." (PMID 24770346, 2014). "Thus, this system might be likely to reflect the activation of endogenous Rac1 mainly in the patients’ tumor tissues, although activation of other Rac members, such as Rac2 and Rac3 and/or Cdc42 cannot be ruled out." (PMID 35110666, 2022). "However, there has not been a report of application of RAC2 in tumor radiosensitization." (PMID 31281584, 2019).
infection (21 papers, 2011 to 2025). The state of being infected such as from the introduction of a foreign agent such as serum, vaccine, antigenic substance or organism. "It is interesting that Rac2-knockout animals or zebrafish expressing a dominant negative form of Rac2 in neutrophils are more susceptible to infections." (PMID 28954734, 2017). "However, it was recently reported that macrophage-specific Rac2 rescues control of invasive hyphal growth by A. fumigatus in pan-Rac2 deficient fish during hindbrain infection." (PMID 40197062, 2025). "The infection induced upregulation of chemoattractant (cklf) and respiratory burst effectors (rac2 and mpx), while suppressing inflammatory mediators (il8, tlr5, and clec4el)." (PMID 40821846, 2025). "This is consistent with the research result that rac2 gene expression is significantly upregulated in fruit fly (Drosophila melanogaster) upon pathogen infection." (PMID 41516313, 2025). "As observed previously, rac2−/− larvae succumbed to the infection at a significantly higher rate than rac2+/+ or rac2+/− larvae." (PMID 38168666, 2024). "In Arabidopsis, Rac2/Rop7 was found to play a role in xylogenesis, while in tomato, it was found to be involved in plant immune response to pathogen infection." (PMID 38794426, 2024). "In Sca-1 KO mice, Rac2 was generally sequestered in the cytosol of cells following septic infection." (PMID 38665923, 2024). "We therefore aimed to further characterize the function of macrophages against A. fumigatus in an in vivo vertebrate infection model by live imaging of the macrophage behavior in A. fumigatus-infected rac2 mutant zebrafish larvae." (PMID 38168666, 2024). "The infection rates of RhoA and Rac1 silenced cells were about 65% of that of the mock cells, while the infection rate of RhoA and Rac2 double-silenced cells was about 50% of that of the mock cells." (PMID 23721065, 2013). "A naturally occurring dominant negative mutation in Rac2 has been found in a patient with severe recurrent infection and reduced neutrophil chemotaxis, emphasising the importance of Rac2′s function in the human immune system." (PMID 21387015, 2011). "We also tracked the survival of these imaged larvae, confirming that even in the absence of functional neutrophils, Rac2 deficiency leads to significantly decreased larval survival after infection." (PMID 38168666, 2024). "We also wondered if macrophage-specific rescue of Rac2 expression in rac2−/− larvae could promote larval survival and control of fungal growth after infection." (PMID 38168666, 2024). "Additionally, Rho GTPases, such as Cdc42, Rac1 and Rac2, regulate phagocytosis by altering hemocyte cell shape after infection." (PMID 30518379, 2018). "We previously demonstrated that the absence of Rac2 completely impairs the ability of neutrophils to migrate to sites of infection or wounding, and thus, a major cause of the susceptibility of these larvae to A. fumigatus infection is likely to be a lack of neutrophil-mediated killing." (PMID 38168666, 2024). "In this study, we utilized this larval zebrafish model to determine the function of Rac2 in macrophages against A. fumigatus, taking advantage of the live imaging capabilities of this model to visualize the requirement for Rac2 in macrophage responses in live intact hosts over a multi-day infection." (PMID 38168666, 2024). "While Rac2-deficient zebrafish larvae are susceptible to A. fumigatus infection, Rac2 deficiency does not impair macrophage migration to the infection site, interaction with and phagocytosis of spores, spore trafficking to acidified compartments, or spore killing." (PMID 38168666, 2024). "Rac2 activity and Ca2+ flux tightly regulate the mobilization and exocytosis of primary granules from neutrophils, and our experiments reveal that chemical inhibition of either Rac2 activation or Ca2+ flux is sufficient to inhibit neutrophil primary granule release during Y. pestis ΔyopEH infection." (PMID 31822588, 2019).
infection (continued). "Unlike Rac2 D57N larvae, Irf8 morphants also had increased susceptibility to cpsA infection, supporting the importance of macrophages for controlling S. iniae infection and suggesting that neutrophils and macrophages perform non-redundant functions in host defense against S. iniae." (PMID 28658259, 2017). "Therefore, Rac2 may regulate threonine phosphorylation of coronin, which may facilitate the coordination of multiple immune cell functions including polarization towards infection which is critical for both chemotaxis and degranulation." (PMID 22081935, 2011). "Surprisingly, we find that Rac2 is not required in macrophages for earlier responses to the infection, including cell migration, phagocytosis, phagosomal acidification, and spore killing." (PMID 38168666, 2024). "Furthermore, phagocyte recruitment to the site of infection is accompanied by a macrophage-dependent local upregulation of TNFα when neutrophils are disabled (Rac2-D57N) but not when neutrophils are functional." (PMID 32776983, 2020). "In addition, Rac2 is an essential subunit for the phagocyte NADPH oxidase complex, directly interacting with gp19phox and p67phox, and is responsible for the generation of superoxide ions during infection." (PMID 28954734, 2017). "Thus, YopH appears to play a major role in protecting Yptb from ROS production during tissue infection, in part through its ability to block SKAP2-controlled pathways, while YopE may play a more prominent role at the phagocytic cup in inactivating Rac1 and RhoG rather than in inactivating Rac2." (PMID 32392230, 2020).